LCE3B (late cornified envelope 3B)
Description:
A structural component of the cornified envelope of the stratum corneum involved in innate cutaneous host defense (Probable). Possesses defensin-like antimicrobial activity against a broad spectrum of Gram-positive and Gram-negative bacteria, both aerobic and anaerobic species. Upon inflammation, may regulate skin barrier repair by shaping cutaneous microbiota composition and immune response to bacterial antigens.
Synonyms: LEP14
Tractability: No criterion of Open Targets' tractability assessment is met for any kind of drug.
Gene: Protein-coding gene on chromosome 1 (152,613,811 to 152,614,098, forward strand). Ensembl gene ENSG00000187238.
Pathways (Reactome):
Developmental Biology: Formation of the cornified envelope
Gene Ontology:
Molecular function: protein binding
Biological process: defense response to Gram-negative bacterium; defense response to Gram-positive bacterium; killing of cells of another organism; epidermis development
Homologues: Orthologues: chimpanzee LCE3B (96% identical), pig LCE3B (79% identical). Paralogues in human: LCE3C (79% identical), LCE3D (79% identical), LCE3E (77% identical), LCE3A (76% identical), LCE2D (61% identical), LCE1E (60% identical), LCE5A (60% identical), LCE1F (59% identical), LCE2A (59% identical), LCE2B (59% identical), LCE2C (59% identical), LCE1D (56% identical), and 8 more.
Diseases named in the same sentence as LCE3B in open-access papers:
LCE3B is named in the same sentence as 3 diseases in open-access papers, as found by Europe PMC text mining. Sharing a sentence is not in itself a finding about the gene and the disease. The quoted sentences say what the papers report.
psoriasis (21 papers, 2010 to 2024). An autoimmune condition characterized by red, well-delineated plaques with silvery scales that are usually on the extensor surfaces and scalp. "For example, we identified a LOF deletion affecting LCE3B/LC23C gene that is in strong LD with two non-coding GWAS lead SNPs associated with Psoriasis." (PMID 39496583, 2024). "Regarding antimicrobial late cornified envelope proteins, the psoriasis-risk-factor deletion of LCE3B/C genes also affects microbiota composition." (PMID 35888633, 2022). "The Agilent H244K array contains six probes covering the 32 kb deletion involving the LCE3C and LCE3B genes, that has been associated with psoriasis and other autoimmune diseases." (PMID 23594316, 2013). "Genetic variations in ERAP1, IL23R, and LCE3B/LCE3C have recently been associated with pediatric-onset psoriasis (onset < age 18) in a small study." (PMID 24175098, 2013). "In particular, LCE3B and LCE3C deletions are highly implicated as a psoriasis risk factor due to interactions with the HLA-C*06 gene." (PMID 37569685, 2023). "LCE genes, specifically LCE3B and LCE3C, located in the PSORS4 locus, have been shown to be related with psoriasis risk by both copy number variation studies and GWAS." (PMID 37628670, 2023). "Many of the human genes overlapping with ZCRs in our study have known presence/absence variation among human populations, such as LCE3B and LCE3C, which are associated with antimicrobial activity and implicated in psoriasis and wound-healing." (PMID 37179373, 2023). "Other human genes such as LCE3B and LCE3C overlapped ZCRs in some samples, for example, a 30 kb nearly continuous region linked to psoriasis that was identified in the CHM1 haploid genome." (PMID 37179373, 2023). "The deletion of LCE3B and LCE3C genes, responsible for encoding late cornified envelope proteins, is associated with psoriasis." (PMID 35888633, 2022). "It was demonstrated that deletion in late cornified envelope genes, LCE3B and LCE3C, located within PSORS4 is a genetic risk factor of psoriasis, suggesting disruption of the differentiation process in psoriasis." (PMID 35054853, 2022). "Consistent with our observations, deletion within the LCE3B and LCE3C genes (LCE3B_LCE3C) was shown to be associated with an increased risk of developing psoriasis." (PMID 30261611, 2018). "Genetic studies indicate a role for skin barrier dysfunction in psoriasis since deletion of LCE3B and LCE3C genes, encoding stratum corneum proteins involved in terminal differentiation of the epidermis, was found to be associated with psoriasis." (PMID 26573299, 2016). "In psoriasis patients, the majority of whom harbor genomic deletion of LCE3B and LCE3C (LCE3C_LCE3B-del), we propose that certain dietary analogues of 1,25D activate the expression of residual LCE3A/LCE3D/LCE3E genes to compensate for the loss of LCE3B/LCE3C in the deletant genotype." (PMID 29401702, 2018). "A common, 32kb deletion of LCE3B and LCE3C genes is strongly associated with psoriasis." (PMID 27919236, 2016). "There are several polymorphisms associated with risk of psoriasis, including signal transducer and activator of transcription 4 (STAT4), TaqI polymorphisms in vitamin D receptor (VDR) gene, interleukin-10 (IL-10) polymorphisms and LCE3B genes." (PMID 24324571, 2013). "In lesional psoriasis skin, the expression of LCE3A, LCE3B and LCE3C is markedly increased, which is consistent with our findings." (PMID 34440590, 2021). "A small deletion encompassing LCE3B and part of LCE3C (LCE3C_LCE3B-del) is found in a substantial fraction of psoriasis sufferers." (PMID 32539844, 2020). "An association between a common deletion comprising the late cornified envelope LCE3B and LCE3C genes (LCE3C_LCE3B-del) and Psoriasis (Ps) has been reported." (PMID 20331852, 2010). "It is unknown how the lack of LCE3B and LCE3C activity due to their deletion leads to psoriasis susceptibility." (PMID 27919236, 2016).
LCE3B also shares sentences with these, for which no sentence is quoted: atopic dermatitis (1 paper); autoimmune disease (1).